AVP (arginine vasopressin)
Diseases named in the same sentence as AVP in open-access papers (continued):
Sharing a sentence is not in itself a finding about the gene and the disease.
septic shock (17 papers, 2009 to 2025). Shock caused by infection; frequently caused by gram negative bacteria, although some cases have been caused by other bacteria, viruses, fungi, and protozoa; characterized by fever, chills, tachycardia, tachypnea, and hypotension. "The onset of septic shock was associated with an increase in AVP plasma levels as compared with BL in all groups (P < 0.05 versus BL each)." (PMID 21054850, 2010). "Accordingly, the administration of exogenous AVP has been proposed as a therapeutic strategy to restore vascular tone and improve circulatory stability in septic shock." (PMID 41341027, 2025). "Our observation that septic shock patients with longer NE infusion duration prior to AVP initiation were more likely to remain dependent of vasopressor therapy at any given time point during shock aligns with these results, but was less pronounced." (PMID 40299108, 2025). "In patients with vasodilatory shock such as septic shock, AVP has a much more potent effect and is released at the very early phase of shock." (PMID 35677822, 2022). "We therefore postulate that due to the dual stimulation of AVP release in shock states, via endogenous stress and hypotension, we demonstrate highest levels of copeptin in cardiogenic and septic shock patients." (PMID 28118414, 2017). "The difference in baseline plasma AVP levels is likely related to the fact that our two studies were performed at two separate times of septic shock course (i.e. post-acute and recovery phases) during which plasma vasopressin level has been shown to decrease." (PMID 24223220, 2013). "Regarding the first objective, we have previously reported that AVP secretion during an osmotic challenge performed during the post-acute phase (i.e. 3 days from onset) of septic shock is dramatically reduced in half patients." (PMID 24223220, 2013). "Plasma AVP levels have been shown to decrease during septic shock and after 36 hours to be, inappropriately within the normal range despite hypotension in about a third of septic shock patients." (PMID 24223220, 2013). "Vasopressin (AVP) secretion during an osmotic challenge is frequently altered in the immediate post-acute phase of septic shock." (PMID 24223220, 2013). "For example, arginine vasopressin (AVP), which acts on vascular smooth muscle via V1 receptors, has been used as an additional vasoactive drug in patients with septic shock." (PMID 22355305, 2012). "Although AVP exerts minimal vasoconstrictive effects in normotensive individuals, it induces a strong pressor response in hypotensive states, supporting its role as hormone replacement in septic shock." (PMID 41029879, 2025). "Therefore, the primary aim of the current study was to identify patient characteristics additional to NE infusion rates to relate to short-term AVP hemodynamic responsiveness in patients with septic shock." (PMID 40299108, 2025). "We designed a project to determine, in two separate cohorts, whether AVP secretion during an osmotic challenge is altered in the post-acute phase (i.e. 3 days from onset) and after recovery from septic shock, respectively." (PMID 24223220, 2013). "Moreover, experimental studies and clinical studies have provided evidence of a superiority of first-line TP over AVP or sole NE in stabilizing cardiovascular hemodynamics in septic shock." (PMID 21929764, 2011). "Although AVP may contribute to antidiuresis in a dose-dependent manner, recent studies revealed that in the presence of septic shock, vasopressin analogues may increase diuresis and improve renal function." (PMID 19664253, 2009). "Although continuous infusion of low-dose TP in septic sheep and in patients with septic shock also maintained MAP, this approach would make TP almost identical to AVP in terms of hemodynamic and functional effects." (PMID 22355305, 2012).
septic shock (continued). "In hypodynamic models of septic shock, where volume status and cardiac output did not meet the enhanced needs, AVP and vasopressin analogs worsened splanchnic hemodynamics." (PMID 31718715, 2019). "Arginine vasopressin (AVP) and analogs with V1A receptor agonist activity are increasingly used to treat fluid-resistant vasodilatory hypotension, including catecholamine-refractory septic shock." (PMID 27788216, 2016). "In our previous study, AVP secretion did not increase in half of patients osmotically challenged in the post-acute phase of their septic shock (i.e. 3 days after onset)." (PMID 24223220, 2013). "Despite these findings, there remains uncertainty regarding whether AVP, while effectively maintaining MAP, can also improve perfusion of other key organs, especially in this article, the kidneys, and reduce the extent of organ dysfunction in septic shock." (PMID 41341027, 2025). "The major finding of the present study is that in fluid-resuscitated septic shock patients treated with NE to maintain a MAP between 65 and 75 mmHg, the addition of continuously infused low-dose TP and AVP does not affect sublingual microcirculatory blood flow compared with placebo." (PMID 21929764, 2011).
Insulin resistance (16 papers, 2014 to 2025). Increased resistance towards insulin, that is, diminished effectiveness of insulin in reducing blood glucose levels. "Sundry studies have found that increased AVP release (commonly assessed by quantification of the surrogate precursor product copeptin) is associated with insulin resistance, type 2 diabetes and major cardiovascular events that characterise the metabolic syndrome." (PMID 37264028, 2023). "This hypothesis suggests a potential pathogenic connection between AVP and insulin resistance in CKD." (PMID 38255650, 2023). "It is also interesting to recall that the V1a-/- mouse was reported to show insulin resistance and hyperammonemia, due to increased protein catabolism, suggesting that AVP plays a role in regulating the balance between protein synthesis and degradation." (PMID 31461843, 2019). "In recent years, an increasing number of studies have evaluated the role of AVP and the activation of hypothalamic-pituitary adrenal axis by AVP in insulin resistance and metabolic abnormalities." (PMID 27928437, 2016). "The AVP system has also been suggested to contribute to insulin resistance and DM potentially through a variety of mechanisms including stimulation of glucagon and ACTH secretion and glycogenolysis, etc.." (PMID 24628831, 2014). "It should be mentioned that the implication of the AVP pathway in the pathogenesis of MetS and insulin resistance is complex, perhaps involving not only the AVP secretion but also genetic and non-genetic effects of both V1a and V1b receptors in the liver and pancreas." (PMID 27928437, 2016). "Human and animal studies have indicated that the AVP system may play a role in glucose homeostasis, insulin resistance, and lipid and fat metabolism, and vasopressin has been reported to be elevated in patients with type 2 diabetes." (PMID 27312697, 2016). "Insulin resistance and high insulin levels increase insulin-regulated aminopeptidase (IRAP) activity, which accelerates AVP degradation and triggers a compensatory rise in AVP synthesis, potentially contributing to the development of metabolic syndrome." (PMID 40428796, 2025). "It has been suggested that insulin resistance and high insulin levels increase IRAP activity and alter AVP turnover, which leads to increased synthesis of vasopressin, and may play a role in the development of metabolic syndrome." (PMID 39769071, 2024).
metabolic syndrome (16 papers, 2014 to 2025). A cluster of metabolic risk factors for CARDIOVASCULAR DISEASES and TYPE 2 DIABETES MELLITUS. "Obese individuals with metabolic syndrome present high plasma levels of copeptin, a marker of arginine-vasopressin (AVP), which is independently associated with ADPKD progression." (PMID 35208476, 2022). "Work is needed at unraveling the mechanism(s) by which fructose consumption and increased AVP levels can worsen the renal disease associated with components of the metabolic syndrome." (PMID 35656391, 2022). "Fructose is a secretagogue for AVP, and AVP promotes lipogenesis, hyperinsulinemia, and many of the pathophysiological intermediaries associated with the metabolic syndrome." (PMID 35656391, 2022). "This is particularly true in hot, arid lands, such as Mesoamerica where high ambient temperatures and physical exertion, and accordingly high levels of AVP, are associated with the growing prevalence of the metabolic syndrome and the development of chronic kidney disease." (PMID 35656391, 2022). "Arginine vasopressin (AVP) is now being implicated in the development of metabolic syndrome." (PMID 35656391, 2022). "In summary, higher serum copeptin levels, a surrogate for AVP release, are associated not only with systolic and diastolic blood pressure but also with several components of metabolic syndrome including obesity, elevated concentration of triglycerides, albuminuria, and serum uric acid level." (PMID 24375010, 2014). "Several cross-sectional and observational studies have connected elevated AVP or copeptin levels to multiple elements of the metabolic syndrome." (PMID 40428796, 2025). "Further, several studies have repeatedly shown predictive value of copeptin (a stable biomarker of AVP) in relation to the metabolic syndrome, type 2 diabetes, and cardiovascular diseases." (PMID 38241317, 2024). "In summary, there appears to be both metabolic (mediated by V1a receptor-induced gluconeogenesis) and central (mediated by activation of V1b receptors and the stress response) mechanisms by which AVP contributes to hyperglycemia and the metabolic syndrome." (PMID 35656391, 2022). "It has also been shown that the effect of AVP on inducing hepatic lipogenesis and the metabolic syndrome is dependent upon the V1b receptor." (PMID 35656391, 2022). "The potential potentiation of the metabolic syndrome from chronically increased levels of AVP, albeit at low levels, and increased fructose consumption has significant public health implications." (PMID 35656391, 2022). "There are several pathways by which increases in circulating AVP can contribute to the development of the metabolic syndrome." (PMID 35656391, 2022). "Clearly, endogenous fructose production in the brain can contribute to any AVP-dependent pathway that promotes the metabolic syndrome phenotype despite having low plasma concentrations of fructose." (PMID 35656391, 2022). "Further, increased activity of the AVP system has been recognized as a unifying factor in the metabolic syndrome with potential importance in the treatment of cardiovascular disease." (PMID 32210168, 2020). "Moreover, fructose intake has been shown to stimulate AVP secretion to a greater extent than glucose, with high AVP levels in fructose-fed mice leading to the development of metabolic syndrome via V1bR activation." (PMID 40428796, 2025). "Additionally, increased water intake in fructose-fed mice lowers AVP secretion, which, in turn, prevents or ameliorates fructose-induced metabolic syndrome." (PMID 40428796, 2025). "Interestingly, fructose-fed V1bR-deficient mice, despite having elevated copeptin levels, are protected from the development of metabolic syndrome, highlighting a receptor-specific mechanism of AVP signaling." (PMID 40428796, 2025). "Clinical data, based on measurements of blood copeptin concentrations, suggest that AVP may play a role in the pathogenesis of the metabolic syndrome (MetS)." (PMID 39000501, 2024).
metabolic syndrome (continued). "Indeed, over 10 years ago, it was recognized that AVP levels significantly correlated with several markers of the metabolic syndrome, i.e., body mass index, fasting plasma glucose and insulin concentrations, insulin resistance, and triglyceride levels." (PMID 35656391, 2022). "A change in neurochemistry, particularly an increase in arginine vasopressin, as well as a higher incidence of metabolic syndrome, may possibly play a role in poor cardiac outcomes." (PMID 35165641, 2022). "In addition, it was suggested that undesirable environmental factors often impair the circadian rhythm, such as circadian release of AVP, leading to the progression of metabolic syndrome with dysregulation of insulin secretion." (PMID 34960038, 2021). "We review the pathways by which arginine vasopressin (AVP) and hydration influence the sequelae of the metabolic syndrome induced by high fructose consumption." (PMID 35656391, 2022). "Because hydration levels mediate central AVP release and plasma AVP concentrations, it is not surprising that hydration levels have also been shown convincingly to correlate with the presence of the metabolic syndrome." (PMID 35656391, 2022).
type 2 diabetes (16 papers, 2016 to 2025). "People who drink less water have an increased risk of developing type 2 diabetes, and this seems to be associated with elevated AVP levels." (PMID 37264028, 2023). "Thus, the results provided direct evidence that type 2 diabetes is associated with the increased secretion of AVP in the hypothalamic nuclei." (PMID 38279313, 2024). "Studies on Zucker diabetic fatty (ZDF) rats, which serve as an experimental model of type 2 diabetes, demonstrated higher levels of AVP in the PVN and SON of ZDF rats than in the PVN and SON of Zucker lean control (ZLC) rats and the pre-diabetic rats." (PMID 38279313, 2024). "Elevated plasma copeptin (AVP substitute) concentrations have been demonstrated in patients with type 2 diabetes and with type 1 diabetes." (PMID 39000501, 2024). "Expression of AVP mRNA was found to be elevated in the brains of db/db mice, which is a genetic model of type II diabetes." (PMID 39769071, 2024). "Studies on Zucker diabetic fatty rats, which are used as an experimental model of human type 2 diabetes, showed that these rats manifest significantly higher expression of AVP in the PVN and SON than the control rats." (PMID 39769071, 2024). "Recent evidence has suggested a link between body water deficits and impairments in blood glucose regulation, particularly in individuals with type 2 diabetics, attributed to elevations in the fluid regulatory hormone arginine vasopressin (AVP)." (PMID 32825404, 2020). "Arginine vasopressin (AVP) and oxytocin are associated with type 2 diabetes but are new biomarkers for the progression of FT1D." (PMID 33083497, 2020). "Furthermore, many studies have found that increased AVP release (assessed by measuring the surrogate precursor product copeptin) predicts insulin resistance and the onset of type 2 diabetes and major cardiovascular events in metabolic syndrome patients." (PMID 36773648, 2023). "Our data show that type 2 diabetes differentially affects the numbers of AVP- and VIP-expressing neurons and GFAP-ir astroglial cells in the SCN, each of which could affect the daily rhythmicity of the SCN biological clock machinery." (PMID 31327049, 2019). "The loss of AVP-ir and VIP-ir SCN neurons, therefore, could result in a disbalanced autonomic hypothalamic output, as often observed in type 2 diabetes." (PMID 31327049, 2019). "In addition, the relative intensity of AVP immunoreactivity was reduced in the individuals with type 2 diabetes." (PMID 31327049, 2019). "The post-mortem immunohistochemical examination of human hypothalamic tissue revealed significantly lower numbers of AVP immunoreactive neurons and astroglial cells in the SCN of subjects with type 2 diabetes than in the SCN of the control individuals." (PMID 39769071, 2024).
Shock (15 papers, 2006 to 2025). The state in which profound and widespread reduction of effective tissue perfusion leads first to reversible, and then if prolonged, to irreversible cellular injury. "The onset of septic shock was associated with an increase in AVP plasma levels as compared to baseline in all groups." (PMID 21054850, 2010). "The impaired AVP secretion system leads to decreased serum AVP levels, which contributes to the loss of vascular tone and hemodynamic instability in patients with septic shock." (PMID 41341027, 2025). "Additionally, in patients with septic shock, a relative endogenous vasopressin deficiency may exist and fixed, low dose exogenous AVP can be utilized as an endocrine supplement with resultant improvements in hemodynamics." (PMID 29511951, 2018). "The relationship between ER stress in arginine vasopressin neurons and elevated arginine vasopressin levels in cases of hemorrhagic and septic shock has been documented." (PMID 40867920, 2025). "• In ovine septic shock, selective V2-receptor-antagonism supplemented with open-label norepinephrine stabilized cardiovascular hemodynamics as effectively as combined AVP and open-label norepinephrine." (PMID 21054850, 2010). "Infusing arginine vasopressin (AVP) in vasodilatory septic shock is usually accompanied by a decrease in cardiac output and systemic oxygen (O2) transport." (PMID 19591694, 2009). "In septic shock, however, a biphasic response has been recognized, with high levels in the early phase and inappropriately low AVP levels in established septic shock." (PMID 16469127, 2006). "In conclusion, we found alteration of osmoregulation of AVP release, characterized by a dramatic decrease in vasopressin secretion and thirst perception during osmotic challenge, in almost two-third of patients recovering from septic shock." (PMID 24223220, 2013). "Therefore, our results suggest that tapering AVP before NE (rather than the reverse) may lead to a lower incidence of hypotension in patients recovering from septic shock who are on concomitant AVP and NE." (PMID 29784057, 2018).
liver cirrhosis (14 papers, 2015 to 2025). "Desmopressin is more resistant to proteolysis and presents mainly antidiuretic effects, while terlipressin is a long-acting AVP analogue and a drug recommended in the treatment of varicose bleeding in patients with liver cirrhosis." (PMID 35328489, 2022). "In decompensated liver cirrhosis, the pathogenesis of non-osmotic release of AVP is similar to that in heart failure." (PMID 29088071, 2017).
portal hypertension (14 papers, 2012 to 2025). Increased blood pressure in the portal venous system. "The success of the AVP deficiency strategy suggests that blocking AVP receptors may be therapeutically useful to treat inflammatory-fibrotic liver diseases." (PMID 34926704, 2021). "The AVPR1a agonist vasopressin (AVP), or terlipressin, is used in cases of postoperative bowel distention, refractory hypotension after cardiac surgery, intraoperative hypotension, or portal hypertension." (PMID 41375820, 2025). "The cardiovascular hormones renin/angiotensin/aldosterone (RAA), brain-type natriuretic peptide (BNP)and arginine-vasopressin (AVP) are key regulators of systemic circulatory homeostasis in portal hypertension (PH)." (PMID 34021479, 2021). "Additionally, copeptin levels increased in parallel with MASH severity, suggesting a potential role of AVP signaling in liver disease progression." (PMID 40428796, 2025). "It has been demonstrated that abnormal AVP levels could severely promote portal hypertension, which can lead to decreased liver function and hepatic encephalopathy." (PMID 38492309, 2024). "Acute increase in blood BA concentration could stimulate arginine vasopressin (AVP) secretion, which helps to limit portal hypertension and cholestasis." (PMID 25678050, 2015). "Dilutional hyponatremia (HN), due to the non-osmotic release of arginine vasopressin (AVP) into the bloodstream, occurs in 30% of cirrhotics and is associated with severe portal hypertension." (PMID 26237379, 2014). "AVP release in portal hypertension is thought to occur via baroreceptor-mediated nonosmotic stimulation caused by a reduction in effective circulating volume, due in turn to arterial splanchnic vasodilation." (PMID 22732834, 2012).